CCN2 (cellular communication network factor 2)
Diseases named in the same sentence as CCN2 in open-access papers (continued):
Sharing a sentence is not in itself a finding about the gene and the disease.
breast carcinoma (185 papers, 2005 to 2026). "The stimulation of GPR30 by OHT promotes CCN2 proteins in breast cancer associated fibroblasts (CAFs), which contributes to the invasive behavior of breast tumors." (PMID 34940056, 2021). "Overexpression of CCN2/CTGF was associated with invasiveness potential of the lung adenocarcinoma cells, and osteolytic metastasis of breast cancer." (PMID 25120383, 2014). "High CCN1/CCN3 or CCN2/CCN3 mRNA ratios were found to be associated with a highly metastatic phenotype in breast cancer cells." (PMID 22427255, 2012). "CTGF/CCN2 is linked to breast cancer metastasis, where it regulates angiogenesis in a manner that could be further influenced by PTHrP." (PMID 23977121, 2013). "Furthermore, pro-apoptotic effects of CCN2 have been reported in vascular smooth muscle cells and breast cancer cells, although the underlying mechanisms have yet to be understood." (PMID 16303051, 2005). "Our study highlights a potential combination therapeutic modality based on PRL and YAP inhibitors or PRL and anti-CCN2 antibodies in breast cancer." (PMID 40157909, 2025). "To build upon these results and examine its validity in human breast cancer tumor samples, we investigated PRLR and CCN2 gene expression profiles in the breast cancer SCAN-B (n = 3207) and METABRIC (n = 1992) cohorts." (PMID 40157909, 2025). "RNA-Seq data analysis of CRISPR/Cas9 knockout of the PRLR in HR+ breast cancer cells revealed the oncogenic CCN2 gene as the most upregulated target gene, highlighting an antagonistic relationship between PRLR and CCN2 gene expression." (PMID 40157909, 2025). "As visualized in the analysis, CCN1, CCN2 and EDN1 were among the most robustly downregulated genes, and it is notable that all of these genes have been implicated in breast cancer development." (PMID 41145489, 2025). "We have previously reported that biologically active CCN2 stimulates mammosphere formation of MCF-7 mammary carcinoma cells under anchorage-independent growth conditions." (PMID 36529291, 2023). "Estrogenic GPR30 signaling promotes the proliferation and migration in breast cancer cells via CCN2." (PMID 34940056, 2021). "Increased expression of CCN2 leads to an increase of breast cancer metastasis, probably abusing TGF-β and BMP growth factors." (PMID 34940056, 2021). "An increased expression of CCN2 (also known as connective tissue growth factor [CTGF]) protein has been identified in bone metastases of breast cancer compared with normal breast epithelial cells and other metastatic foci." (PMID 34212564, 2021). "CCN2 cooperates in angiogenesis and osteoclastogenesis induced by metastatic breast cancer cells, inducing angiopoietin 2 and RANKL." (PMID 34228239, 2021). "CCN2 mediates osteolytic metastasis of breast cancer via the protein kinase A- and protein kinase C- dependent activation of ERK." (PMID 34940056, 2021). "Comparison of different breast cancer cell lines or parental cells with those experimentally enriched for metastatic potential, invariably highlighted overexpression of CCN2." (PMID 34228239, 2021). "CCN2, as observed in breast cancer, CCN3 and CCN4 levels are up regulated in prostate cancer and bone-metastatic cells or corresponding bone metastasis." (PMID 34228239, 2021). "CCN2/CTGF mRNA expression was higher in breast cancer, head and neck cancer, thyroid cancer, pancreatic cancer, glioma, endometrial cancer, ovarian cancer, renal cancer, compared to testis cancer and other cancer types." (PMID 32260433, 2020). "For example, the level of connective tissue growth factor (CTGF/CCN2) in gastric, pancreatic, and breast cancer is correlated to worse prognosis; however, the opposite effect is seen in ovarian, lung and colorectal cancer." (PMID 28465477, 2017). "In many cancer types, such as osteosarcoma, melanoma and breast cancer, CCN2 is abnormally expressed and involved in tumor progression or chemo-resistance." (PMID 29029514, 2017).
breast carcinoma (continued). "Among the CCN protein family, CCN2 previously was shown to increase migration and angiogenesis in breast cancer cells." (PMID 25732125, 2015). "Previous studies have reported similar nuclear localization of CCN proteins in cancer cells, including nuclear localization of CCN1 in prostate carcinoma and breast cancer cells and the nuclear localization of CCN2 in melanoma cells." (PMID 25541962, 2014). "Many studies have confirmed that CCN2 has a higher level of expression in lung cancer, pancreatic cancer, breast cancer, chondrosarcoma, and melanomas than in normal tissues." (PMID 24637722, 2014). "In breast cancer, CCN2 expression confers resistance to chemotherapeutic agents through augmenting a survival pathway." (PMID 24637722, 2014). "An in vivo mouse model study was performed to investigate the role of CCN2 in osteolytic metastasis by breast cancer cells." (PMID 24551846, 2014). "Indeed, CCN2 has been reported to promote tumorigenesis in many cancer types, including pancreatic cancer, prostate cancer, lung cancer, breast cancer among others." (PMID 40157909, 2025). "Furthermore, ectopic expression of CCN2 in breast cancer cell lines also stimulates angiogenesis and migration, where the CT domain of CCN2 protein plays a pivotal role." (PMID 34940056, 2021). "CCN2 also promotes angiogenesis in breast cancer and osteosarcoma." (PMID 29029514, 2017). "Interestingly, CCN2/CTGF enhanced the motility of breast cancer cells by an integrin-α5β3-ERK1/2-phosphorylation." (PMID 25120383, 2014). "A homozygous deletion of CCN2/CTGF at human chromosome 6q23.2 by hypermethylation could be used or breast cancer cells, for example." (PMID 25120383, 2014). "Another previously published study investigated the mechanism of osteolytic bone metastasis by selecting human breast cancer cell line subpopulations with elevated metastatic activity and found that IL-11 and CCN2 expressions were further increased by the prometastatic cytokine TGFβ." (PMID 24551846, 2014). "This is in contrast to our findings in which we observed high CCN3 levels in the context of low CCN1 and CCN2 expression in bone metastatic breast cancer cells and also contrasts with the observation that human breast cancer bone metastases that display high CCN3 mRNA expression." (PMID 22427255, 2012). "For example, CCN2 expression could even be enhanced by impaired glycolysis in breast cancer cells." (PMID 35682564, 2022). "The negative regulation of tumour cells on CCN2 and type I collagen gene expression in fibroblasts may therefore be more likely to occur during the invasive stages of breast cancer, when tumour cells are in close contact with surrounding fibroblasts as a result of basement membrane degradation." (PMID 24090133, 2013). "To elucidate the role CCN2 in regulating/altering PRL/PRLR effects in mammary and breast cancer cells, we first generated CCN2 physical interaction gene network." (PMID 40157909, 2025). "These analyses emphasize CCN2 gene as part of the Hippo pathway and implicate Hippo pathway in regulating PRL differentiation effects in breast cancer." (PMID 40157909, 2025). "In contrast, in another study with a cohort with 122 breast cancer cases, both CCN2 and CCN3 levels were rather repressed in aggressive breast cancer tissues compared to those in the normal ones." (PMID 35682564, 2022). "CCN1 and CCN2 are up regulated in breast cancer and their expression correlates with staging and local (CCN1) or bone (CCN2) invasiveness." (PMID 34228239, 2021). "In contrast with the prometastatic role of CCN1 and CCN2, CCN6 acts as an oncosuppressor in breast cancer, preserving epithelial differentiation." (PMID 34228239, 2021). "CCL4 binding to CCR5 on bone marrow fibroblasts stimulates their release of connective tissue growth factor/CCN2, which supports breast cancer cell growth in bone." (PMID 34745140, 2021).
breast carcinoma (continued). "CCN1, CCN2 and CCN4 are expressed at elevated levels in advanced breast cancers; increased CCN1 levels are thought to lead to more invasive breast cancers." (PMID 18789696, 2008). "In breast cancer, the TAZ-TEAD-CCN1/CCN2 signaling axis plays a crucial role in taxol resistance." (PMID 40234387, 2025). "Moreover, YAP, CCN2 (CTGF) and CCN1 (Cyr61) were also found to be overexpressed in tamoxifen-resistant breast cancer and induced transcriptional repression of ERα." (PMID 40157909, 2025). "While the expression of CCN proteins varies in different cancer types, CCN1, CCN2, CCN3 and CCN4 participate in tumor development and act as oncogenes, but CCN1, CCN3, CCN5, and CCN6 inhibit tumor growth and play tumor-suppressive roles in breast carcinomas." (PMID 34940056, 2021). "The pro-tumorigenic CCN1, CCN2, CCN3, and CCN4 may lead to human breast cancer, although the anti-tumorigenic actions of CCN5 and CCN6 are also present." (PMID 34940056, 2021). "CCN1, CCN2, CCN3, and CCN4 are pro-tumorigenic and may be responsible for human breast carcinoma; while CCN1, CCN3, CCN5 and CCN6 have anti-tumorigenic effects." (PMID 34940056, 2021). "The expression of connective tissue growth factor (CTGF/CCN2) gene is triggered in BM by PTHrP and TGF-β released by breast cancer cells through PKA-PKC-dependent activation of the ERK1/2 pathway, augmenting osteoclastogenesis by binding αvβ3 integrin on OCL progenitors." (PMID 25147739, 2014). "We therefore conclude that breast cancer cells require close contact with fibroblasts in order to upregulate Smad7 which, in turn, leads to decreased ERK signalling resulting in diminished expression of the stromal proteins CCN2 and type I collagen." (PMID 24090133, 2013). "Indeed, we noted that treatment of breast cancer cells with tryptase affected the chromatin accessibility in several regions, including reduced chromatin accessibility in regions containing genes whose transcription were suppressed by tryptase (e.g., CCN1, CCN2)." (PMID 41145489, 2025). "However, an opposite pattern was identified for other of them (VEGFR2/KDR, CYR61/CCN1, IGFBP1, IGFBP4, IGFP6) and no changes for CTGF/CCN2, and IGFP6 across the breast cancer subtypes." (PMID 33531624, 2021).
renal fibrosis (183 papers, 2007 to 2025). A final common manifestation of a wide variety of chronic kidney diseases characterized by glomerulosclerosis and tubulointerstitial fibrosis. "The identification of positive senescent TECs in chronic FAN and its absence in CCN2-deficient mice support the key role of CCN2 in the induction of tubular senescence, secondary senescence, and renal fibrosis." (PMID 40362638, 2025). "The present data confirm and extend previous studies in CCN2-deficient mice, demonstrating the key role of CCN2 in renal fibrosis following IRI, FAN, and chronic graft dysfunction." (PMID 40362638, 2025). "Our findings clearly show that CCN2 deficiency protects against renal fibrosis induced by a nephrotoxic agent, in part by inhibition of cellular senescence." (PMID 40362638, 2025). "More recently, studies in CCN2 conditional deficient mice have demonstrated the role of CCN2 in renal fibrosis, cell growth arrest, oxidative stress, and senescence." (PMID 35204752, 2022). "CCN2 expression is associated with a variety of fibrotic diseases, including renal fibrosis." (PMID 37440209, 2023). "It has previously been demonstrated that suppressing CCN2 expression in tubular epithelial cells can mitigate renal fibrosis after UIRI in a mouse model." (PMID 41380965, 2025). "Overall, our study revealed that SIRT4 inhibition can alleviate the progression of renal fibrosis by suppressing CCN2 expression." (PMID 39495216, 2024). "Previous studies using CCN2 knockout mice demonstrated that the key role of CCN2 in renal fibrosis was via the induction of cell cycle arrest in chronic FA nephropathy and via the activation of cell senescence in IRI kidney damage." (PMID 37627536, 2023). "As renal fibrosis is a terminal pathological situation of diabetes, antagonists of CCN2 were expected as therapeutic agents of this severe and common complication of diabetes in humans." (PMID 35682564, 2022). "It was widely recognized that CCN2 is involved in renal fibrosis, which has been confirmed by several later studies as well." (PMID 35682564, 2022). "CCN3/NOV is known to have an anti-fibrotic action in renal fibrosis models, downregulating CCN2/CTGF and decreasing the expression and accumulation of ECM proteins." (PMID 34063397, 2021). "Remarkably the level of CCN2 expression was shown to be related with the severity and progression of renal fibrosis and it was proposed to be a useful molecular marker for the fibrotic response." (PMID 26421309, 2015). "The overproduction of CCN2 is suggested to play a pivotal role in some fibrotic diseases, including renal fibrosis." (PMID 26421309, 2015). "The present findings contribute to a better understanding of the CCN2 biology and reinforce the importance of its role as a driver of renal fibrosis and vascular rarefaction, mainly mediated by the activation of cellular senescence and favoring the AKI-to-CKD transition and renal damage progression." (PMID 40362638, 2025). "Furthermore, studies employing a specific conditional deletion of CCN2 in tubular cells have shown a reduction in renal fibrosis in experimental IRI, remarking that TECs are important target cells of CCN2 actions in the kidney." (PMID 40362638, 2025). "Collectively, these results suggest that PKM2 regulates TEAD2 expression and may contribute to renal fibrosis progression by modulating CCN2 expression in tubular epithelial cells through the formation of transcriptional complexes with YAP1 and β-catenin." (PMID 41380965, 2025). "In 2004, the role of CCN2 in UUO-induced renal fibrosis was proven by Yokoi and colleagues." (PMID 37440209, 2023). "In conclusion, dexamethasone treatment attenuates the development of renal fibrosis after an acute ischemic event, as evidenced by decreased upregulation of collagen I and Ccn2 gene expression and decreased collagen I immunostaining immediately after a 3-week treatment period." (PMID 30509215, 2018).
renal fibrosis (continued). "Furthermore, we report that the extent of renal fibrosis, in terms of Col I, TGFβ, CCN2 and CCN3 expression and collagen I immunostaining, increases with increasing body temperature during ischemia and ischemia-time." (PMID 27007127, 2016). "The Cellular Communication Network Factor 2 (Ccn2) is a component of the extracellular matrix (ECM), involved in cellular signaling and related to renal fibrosis." (PMID 38791453, 2024). "Connective tissue growth factor (CTGF/CCN2), TGF-β1, IL-6, and sonic hedgehog (SHH) are all key regulators of renal fibrosis." (PMID 36304156, 2022). "Comparable to CCN3/NOV in renal fibrosis, and opposite to fibrotic CCN2/CTGF, CCN5/WISP-2 is anti-fibrotic in the heart." (PMID 34063397, 2021). "As a possible therapeutic target for kidney diseases, YAP inhibition using verteporfin effectively decreased renal fibrosis in mice, reducing TGF-β signaling and CCN2/CTGF levels." (PMID 34063397, 2021). "Cellular communication network factor 2 (CCN2) is a component of the SASP that induces senescence in cultured tubular cells, is involved in experimental renal fibrosis following IRI- and FA-AKI and can activate the RIKP3/NLRP3 pathway in the acute phase of FA-AKI." (PMID 38077379, 2023). "In adult mice, tamoxifen-dependent CCN2 deletion ameliorated renal fibrosis, but it did not improve cardiac fibrosis and hypertrophy." (PMID 35008801, 2021). "In this study, we demonstrated that PKM2 serves as a cofactor in the regulation of CCN2 expression and may contribute to the progression of renal fibrosis by regulating YAP-TEAD and CCN2 expression in proximal tubular epithelial cells by forming transcriptional complexes of YAP1 and β-catenin." (PMID 41380965, 2025).
diabetes (89 papers, 2007 to 2025). "In the fa/fa Zucker rat model of obesity and diabetes caused by leptin receptor deficit, CCN2 mRNA and protein were enhanced by 35 weeks of age in fa/fa rats but not in lean fa/fa littermates." (PMID 37629004, 2023). "CCN2 is implicated in a number of end-organ complications in diabetes, especially in tissues where accumulation of ECM components occurs including the kidney in nephropathy, and the heart in cardiomyopathy." (PMID 35038159, 2022). "CCN2 also caused epithelial to mesenchymal transition (EMT) in renal tubular cells in diabetes, leading to genesis of new fibroblasts in the renal interstitium." (PMID 26421309, 2015). "In considering potential mechanisms for transcript downregulation, we perfomed qRT-PCR for Tgfb1, Tnfa and Ccn2, three genes well-established for their roles in the development of diabetes complications." (PMID 39582036, 2024). "Based on prior studies, the transcriptional activation and full fibrogenic actions of CCN2 likely require the presence of injury-related pathways such as steatosis, inflammation, diabetes, or other metabolic disorders." (PMID 37629004, 2023). "This in vivo study indicates that CCN2 is a molecular target in NASH with high fat diet and diabetes, and that regulation of ERK signalling is implicated in this process." (PMID 35038159, 2022). "In this context, CCN3, which is a CCN family member with molecular functionalities counteracting CCN2, needs to be investigated, as the hormonal function of CCN3 and its association with obesity, diabetes, and insulin resistance were pointed out." (PMID 35955724, 2022). "Data demonstrated that targeting CCN2 bioactivity by the CCN2Ab for 10 weeks provided some protective effects against NASH induced by high fat feeding with diabetes, particularly in inflammation markers and in fibrosis end-points." (PMID 35038159, 2022). "In previous studies published by our laboratory, CCN2 was reported to be upregulated in a clinically relevant murine high fat fed and diabetes NASH experimental model." (PMID 35038159, 2022). "Blocking CCN2 by CCN2Ab showed a trend only to normalisation of the CCN3 gene expression in diabetes alone and HFD alone groups, whereas CCN3 was clearly statistically significantly induced in the HFD + DM group." (PMID 35038159, 2022). "It is known that CCN2 interacts with other growth factors involved in diabetes complications such as TGF-β1." (PMID 26421309, 2015). "CCN2 prevented matrix degradation through increasing the tissue inhibitor of matrix metalloproteinases 1 (TIMP-1) expression in diabetes." (PMID 26421309, 2015). "In addition, endothelial cells specifically overexpress connective tissue growth factor CTGF (Ccn2), which is related to the pathogenesis of microvascular complications in diabetes." (PMID 36533134, 2022). "Although CCN2 is decreased along with adipocyte differentiation, its expression level is found to be increased in the fat tissues of the model mice of obesity and diabetes." (PMID 35682564, 2022). "It was reported that Rho/Rho-kinase pathway correlated with the increase of transforming growth factor-beta (TGF-β) and connective tissue growth factor (CCN2) in diabetes, and the RhoA/Rho-kinase was activated in diabetic db/db mice and rat mesangial cells (MCs) exposed to high glucose." (PMID 26421309, 2015). "Moreover, spironolactone treatment reduced urinary protein and albumin excretion and prohibited the glomerulosclerosis which correlated with reduction of CCN2, type I and type IV collagen expression in type 2 diabetes mellitus rat model." (PMID 26421309, 2015). "CCN2/CTGF, NT-proBNP, age, serum albumin, MHD vintage, high-sensitivity C-reactive protein, smoking, and diabetes mellitus were significant predictors." (PMID 41373510, 2025). "Increased levels of CCN2/CTGF have also been observed in conditions such as myocardial infarction, hypertension, and diabetes." (PMID 35629393, 2022).